SMUG1 (single-strand-selective monofunctional uracil-DNA glycosylase 1)
Description:
Recognizes base lesions in the genome and initiates base excision DNA repair. Acts as a monofunctional DNA glycosylase specific for uracil (U) residues in DNA with a preference for single-stranded DNA substrates. The activity is greater toward mismatches (U/G) compared to matches (U/A). Excises uracil (U), 5-formyluracil (fU) and uracil derivatives bearing an oxidized group at C5 [5-hydroxyuracil (hoU) and 5-hydroxymethyluracil (hmU)] in ssDNA and dsDNA, but not analogous cytosine derivatives (5-hydroxycytosine and 5-formylcytosine), nor other oxidized bases. The activity is damage-specific and salt-dependent. The substrate preference is the following: ssDNA > dsDNA (G pair) = dsDNA (A pair) at low salt concentration, and dsDNA (G pair) > dsDNA (A pair) > ssDNA at high salt concentration.
Synonyms: UNG3; FDG; HMUDG
Tractability: PROTAC: ubiquitination databases record sites on it; its protein half-life has been measured.
Target class: Enzyme; Hydrolase
Gene: Protein-coding gene on chromosome 12 (54,121,277 to 54,189,008, reverse strand). Ensembl gene ENSG00000123415.
Subcellular location: Nucleus
Subcellular location (Human Protein Atlas): Nucleoplasm; Cytosol; Nucleoli fibrillar center
Pathways (Reactome):
DNA Repair: Cleavage of the damaged pyrimidine; Displacement of DNA glycosylase by APEX1; Recognition and association of DNA glycosylase with site containing an affected pyrimidine
Gene Ontology:
Molecular function: DNA N-glycosylase activity; protein binding; single-strand selective uracil DNA N-glycosylase activity; uracil DNA N-glycosylase activity; oxidized pyrimidine nucleobase lesion DNA N-glycosylase activity
Biological process: base-excision repair; depyrimidination
Cellular component: fibrillar center; nucleolus; nucleoplasm; nucleus
Genetic constraint (gnomAD): Loss-of-function variants: 13 observed, 25.23 expected, observed/expected ratio (o/e) 0.52, 90% interval 0.33 to 0.82. The upper end of that interval is the gene's LOEUF score, 0.82, which puts it in group 3 of 6, group 1 being the genes least tolerant of losing a copy. Missense variants: 313 observed, 348.83 expected, observed/expected ratio (o/e) 0.9, 90% interval 0.82 to 0.99. Synonymous variants: 133 observed, 141.43 expected, observed/expected ratio (o/e) 0.94, 90% interval 0.82 to 1.09.
Homologues: Orthologues: chimpanzee SMUG1 (99% identical), macaque SMUG1 (97% identical), pig SMUG1 (93% identical), rabbit SMUG1 (91% identical), guinea pig SMUG1 (91% identical), mouse Smug1 (89% identical), rat Smug1 (87% identical), dog SMUG1 (66% identical), tropical clawed frog smug1 (59% identical), zebrafish smug1 (58% identical), Drosophila melanogaster Smug (39% identical).